G6PD (glucose-6-phosphate dehydrogenase)
Diseases named in the same sentence as G6PD in open-access papers (continued):
Sharing a sentence is not in itself a finding about the gene and the disease.
cancer (continued). "Glucose-6-phosphate dehydrogenase and 6-phosphogluconate dehydrogenase are, therefore, therapeutic targets in cancer." (PMID 33937017, 2021). "Elevated levels of NRF2 in cancer induce the upregulation of glucose 6-phosphate dehydrogenase (G6PD), transketolase (TKT), 6-phosphogluconate dehydrogenase (PGD), and other metabolic enzymes." (PMID 33808001, 2021). "Blocking the glycosylation of G6PD, the rate-limiting enzyme of the pentose phosphate pathway, can reduce the proliferation of cancer cells in vitro and tumor growth in vivo." (PMID 34778244, 2021). "A few studies have revealed that upregulation of G6PD promotes cancer progression in several types of carcinoma." (PMID 33672990, 2021). "PI3K/AKT signaling also plays a similar role in regulating TRIM21 expression and G6PD protein levels in human cancers." (PMID 32312982, 2020). "PGK1 and G6PD, as crucial metabolic markers of glycolysis and the pentose phosphate pathway, have been demonstrated to favor metastasis of various cancers." (PMID 32028979, 2020). "Emerging evidence suggests that G6PD, a gatekeeper of the pentose phosphate pathway, is a potential therapeutic target in human cancers." (PMID 33197892, 2020). "We examined tumour samples obtained from 105 OSCC patients and further explored the role of G6PD in cancer metastasis in vitro and in vivo." (PMID 32719549, 2020). "Glucose 6-phosphate dehydrogenase (G6PD) serves key roles in cancer cell metabolic reprogramming, and has been reported to be involved in certain carcinogenesis." (PMID 33041664, 2020). "Several signaling pathways have been identified to be responsible for promoting G6PD expression or activity in cancer cells." (PMID 32582032, 2020). "It is also found that G6PD is highly expressed in many cancer cells and is closely related to some biological characteristics." (PMID 32596991, 2020). "The relevant role of pentose phosphate pathway (PPP) in cancer metabolic reprogramming has been usually outlined by studying glucose-6-phosphate dehydrogenase (G6PD)." (PMID 33335166, 2020). "G6PD is an interesting metabolic target for cancer therapeutics, and DHEA is widely used for PPP inhibition." (PMID 32487689, 2020). "The G6PD competitive inhibitor, 6-aminonicotinamide (6-AN) is being used to target cancer cells with increased PPP activity and has shown antineoplastic effects." (PMID 31817676, 2019). "Although the relationship between G6PD and cancer is unclear, G6PD is involved in transformation and angiogenesis." (PMID 30661088, 2019). "The present review aims to update the existing knowledge concerning G6PD and emphasizes how G6PD modulates redox signaling and affects cell survival and demise, particularly in diseases such as cancer." (PMID 31500396, 2019). "Aberrant activation of G6PD leads to enhanced cell proliferation and adaptation in many types of cancers." (PMID 31500396, 2019). "On the other hand, G6PD overexpression is common in several cancers and correlates with aggressiveness and poor prognosis." (PMID 30987650, 2019). "G6PD is highly expressed in human liver infected by the Hepatitis B virus (HBV) and HBV-associated cancer." (PMID 31500396, 2019). "G6PD inhibition by polydatin induces endoplasmic reticulum stress and deregulates autophagy flux in cancer cells." (PMID 31500396, 2019). "Using the backbone of the inhibitor to develop a novel and powerful G6PD inhibitor has become an important issue in cancer therapeutics." (PMID 31500396, 2019). "Overexpression and modification of G6PD promotes tumor growth and leads to a poor clinical outcome, while suppression of G6PD inhibits cancer development." (PMID 30661088, 2019). "Rapidly growing cancer cells have evolved myriad mechanisms to activate G6PD for supporting the cellular requirements for NADPH production and fatty acid and nucleic acid synthesis." (PMID 31500396, 2019).
cancer (continued). "The current review provides an update of the existing knowledge concerning G6PD and focuses on how G6PD is involved in redox signaling and how it affects cell survival and death, particularly in diseases such as cancer." (PMID 31500396, 2019). "On the other hand, G6PD inhibition synergistically increased lapatinib-induced cytotoxic effect on cancer cells, while autophagy blockade abolished this effect." (PMID 30987650, 2019). "G6PD inhibition synergistically increases the cytotoxic effect of lapatinib in cancer cells, which can be abolished upon autophagy inhibition." (PMID 31500396, 2019). "Disrupting the interaction between G6PD and these proteins can inhibit the reprogramming of glucose toward the PPP and impair the biosynthesis of the building blocks of cancer cells associated with a decrease in intracellular NADPH." (PMID 31500396, 2019). "Particularly, G6PD is dynamically O-GlcNAcylated in response to hypoxia, and blocking G6PD glycosylation reduces cancer cell proliferation in vitro and in vivo, most likely through energetic unbalance." (PMID 31157165, 2019). "Drug-resistant cancer cell lines display increased G6PD activity and increased intracellular glutathione concentrations indicative of oxidative PPP." (PMID 31500396, 2019). "Glucose-6-phospate dehydrogenase (G6PD) is the limiting enzyme of the pentose phosphate pathway (PPP) correlated to cancer progression and drug resistance." (PMID 30987650, 2019). "Because cancer progression is complicated with the participation of multiple factors, the role of G6PD in carcinogenesis needs to be further delineated." (PMID 29317613, 2018). "We also observed an up-regulation of G6PD, an enzyme that acts on the first step of the pentose phosphate pathway, an extremely important pathway for cancer cells that generates the phosphate required for nucleic acid synthesis." (PMID 30242167, 2018). "The first enzyme of the oxidative phase of the PPP, glucose-6-phosphate dehydrogenase (G6PD), is induced by HIF1α in several different cancer cell lines." (PMID 30374347, 2018). "G6PD inhibitor was further revealed to exert anti-proliferation and cytotoxic effect on cancer cells." (PMID 29445340, 2018). "The PGK1/G6PD-marked hypermetabolic CTCs (GM+CTCs) are promising biomarkers for the diagnosis of cancer metastasis." (PMID 29954422, 2018). "On the other hand, G6PD expression has been shown to be elevated in cancers and its activity induced by oncogenic signaling." (PMID 30181873, 2018). "Other identified targets in our analysis, notably PGD and G6PD from the pentose phosphate pathway, are also predicted to have both anti-proliferative and anti-Warburg effects on cancer." (PMID 30065243, 2018). "While 1,25(OH)2D3 treatment did not dampen the significant reduction in cell survival in response to G6PD knockdown, the inhibitory (anti-cancer) effect of DHEA was found to be enhanced in the presence of 1,25(OH)2D3." (PMID 30181873, 2018). "Glucose-6-phosphate dehydrogenase (G6PD), which catalyzes the first step of the PPP, is upregulated in numerous cancer cells, underlining the importance of the PPP in cancer metabolism." (PMID 30456204, 2018). "Here we have studied the effects of polydatin on G6PD activity, ROS levels, ER stress, and programmed cell death, and its role in inhibiting cancer cell proliferation and invasion both in vitro and in vivo." (PMID 29760380, 2018). "Cancer cells often express relatively high levels of G6PD to match the needs of rapid proliferation." (PMID 29445340, 2018). "Experimental and clinical studies have demonstrated the pivotal role of PGK1 and G6PD in cell malignance and cancer metastasis." (PMID 29954422, 2018). "An increase in G6PD activity is observed in most cancer cell lines, and this promotes cell proliferation." (PMID 29317613, 2018). "Many cancer cells increase the PPP flux via activation of glucose 6-phosphate dehydrogenase (G6PD), the enzyme catalyzing the first reaction of this pathway." (PMID 29245936, 2017).
cancer (continued). "In total, 27 key metabolic enzymes were quantified in our study, including PCK2, PDH and G6PD, which are important for cancer development and progression." (PMID 28378759, 2017). "Glucose-6-phosphate dehydrogenase (G6PD) is an oncoprotein that is overexpressed in cancer cells to provide the NADPH required for their increased anabolism." (PMID 29955429, 2017). "Glucose 6-phosphate dehydrogenase (G6PD) is another important enzyme of PPP pathway which promotes cancer formation by providing NADH." (PMID 29158891, 2017). "This review will summarize the observations regarding the involvement of the PPP in cancer, in particular the role of glucose-6-phosphate dehydrogenase (G6PD) and its relevance for possible therapeutic approaches." (PMID 28553614, 2017). "G6PD's activity is promoted by multiple oncogenic pathways upregulated in cancer, and multiple studies have proposed that G6PD has pro-oncogenic activities." (PMID 28744456, 2017). "We believe that this study warrants further investigation to explore the potential of G6PD inhibition as a cancer treatment strategy and/or biomarker of prognosis." (PMID 29290982, 2017). "Here, the authors show that Plk1 activates the pentose phosphate pathway in cancer cells by directly phosphorylating glucose-6-phosphate dehydrogenase (G6PD) and that such activation is critical for cell cycle progression and cancer cell growth." (PMID 29138396, 2017). "As the PPP is activated, G6PD is usually considered the pacesetter for nicotinamide adenine dinucleotide phosphate (NADPH) production in cancer cells." (PMID 29312589, 2017). "Thirdly, tea polyphenols can inhibit activities of enzyme, including DNA methyltransferase, dihydrofolate reductase, glucose-6-phosphate dehydrogenase, and glyceraldehyde-3-phosphate dehydrogenase, thus preventing cancer formation." (PMID 28454105, 2017). "G6PD activity increases in cancer cells and its inhibition results in decreased cell proliferation and induction of apoptosis." (PMID 28930221, 2017). "This fact has repeatedly been confirmed in more recent studies indicating that G6PD plays an important role in the metabolism of cancer cells." (PMID 27872579, 2016). "The crucial role of the PPP in sustaining cancer cells proliferation was confirmed using siRNAs against glucose-6-phosphate dehydrogenase, the first and rate-limiting enzyme of the PPP." (PMID 26543237, 2016). "qRT-PCR revealed that decreased miR-1 expression and increased G6PD levels correlated with cancer development and malignant characteristics." (PMID 27861141, 2016). "Enzymes within this pathway, including glucose-6-phosphate dehydrogenase (G6PD) and transketolase have been proposed as tumor oncogenes, suggesting that their control is de-regulated in certain cancers." (PMID 27328773, 2016). "At the organismal level, we did not detect any significant increase in the incidence of spontaneous cancers in G6PD-Tg animals." (PMID 26976705, 2016). "Recently discovered roles of G6PD in angiogenesis, cellular proliferation, and resistance to cancer therapy suggest that this protein is likely a major factor in the malignancy process." (PMID 26569310, 2015). "Experiment 2 also indicates that the enhanced activities of hexokinase, PFK1, PFK2 and glucose-6-phosphate dehydrogenase contribute significantly to maintain the altered dynamics in cancer cells." (PMID 26367460, 2015). "G6PD glycosylation was observed in all of these cancer cell lines even though the glycosylation levels were varied, suggesting that G6PD glycosylation is potentially linked to tumor pathology." (PMID 26399441, 2015). "Among these samples, eight pairs showed minimal G6PD expression in either cancer or normal tissues that prevented reliable quantification." (PMID 26399441, 2015). "Blocking glycosylation of G6PD reduces cancer cell proliferation in vitro and impairs tumor growth in vivo." (PMID 26399441, 2015).
cancer (continued). "Among the remaining 31 pairs of samples, 16 pairs showed relatively higher level of glycosylated G6PD in cancer tissues than the matched normal tissues." (PMID 26399441, 2015). "For example, higher level of G6PD have been reported in sera and/or tumor tissues from several cancer patients." (PMID 26581192, 2015). "Interestingly, the clinically relevant inhibitor of glycolysis, 2DG, was found to cause less severe cancer cell cytotoxicity (relative to glucose deprivation), presumably because 2DG can only partially inhibit the pentose cycle since it is still a substrate for G6PD." (PMID 25560241, 2015). "Here, we present evidence that O-GlcNAcylation of G6PD coordinates cancer cell anabolic biosynthesis and redox homoeostasis to promote tumor growth in vivo." (PMID 26399441, 2015). "The function of G6PD is strictly regulated in normal cells but highly activated in cancer cells, making G6PD a strong oncogene candidate." (PMID 24738035, 2014). "This suggests that G6PD supports cancer cell growth in part by regulating the generation of nucleic acid precursors." (PMID 24861463, 2014). "AMPK, which plays a central role in the regulation of cellular energy homeostasis, was also shown to negatively regulate aerobic glycolysis and G6PD expression in cancer cells." (PMID 25015087, 2014). "Previous studies have, also, revealed elevated G6PD activities in malignant tissues in various tissues, suggesting a correlation between G6PD and cancer." (PMID 21037855, 2010). "Decreased G6PD activity through rasburicase could sensitize cancer cells to ferroptosis induced by erastin or RSL3." (PMID 41561226, 2026). "As the initial gatekeeper of the PPP, increased G6PD activity in CRC may protect cancer cells from ferroptosis by maintaining redox homeostasis and supplying intermediates for anabolic reactions to support uncontrolled proliferation." (PMID 41561226, 2026). "G6PD plays an important role in suppressing ferroptosis in cancer." (PMID 41561226, 2026). "Thus, G6PD is essential for rapidly dividing cancer cells, contributing to both nucleotide production and the maintenance of redox homeostasis." (PMID 41514554, 2025). "G6PD has been found to play an oncogenic role in various cancers." (PMID 39472692, 2025). "G6PD is overexpressed in cancers such as breast, liver, colorectal cancer, and leukemia." (PMID 40076506, 2025). "G6PD expression is upregulated in several types of cancer and is related to drug resistance." (PMID 40685383, 2025). "Consequently, abnormal G6PD expression is widely believed to promote tumorigenesis of various human cancers." (PMID 39894218, 2025). "G6PD is found to be overexpressed in cancer cells, which leads to poor survival." (PMID 41244835, 2025). "Importantly, the elevated G6PD activity correlates with poor clinical outcomes and contributes to tumor progression and therapy resistance across multiple cancer types." (PMID 41124013, 2025). "Importantly, treatment with G6PD inhibitor (G6PDi), a G6PDi reduced aggressiveness of PR KD cancer cells." (PMID 41423458, 2025). "Previous studies have reported that the reduced G6PD levels could increase oxidative stress in cancer cells." (PMID 41124013, 2025). "Therefore, the dual regulatory role of G6PD in maintaining redox equilibrium and facilitating metabolic reprogramming serves as a critical determinant in preserving cancer cell stemness under various stress conditions." (PMID 41050691, 2025). "The amount of G6PD frequently has a poor correlation with a patient's prognosis for cancer." (PMID 40956032, 2025).